CD86 (CD86 molecule)
Diseases named in the same sentence as CD86 in open-access papers (continued):
Sharing a sentence is not in itself a finding about the gene and the disease.
glioma (continued). "Markedly higher CD86 expressions were demonstrated in Grade-III glioma with wild-type (WT) isocitrate dehydrogenase (IDH) compared with IDH mutant (P<0.001), while no between-group significance was observed in Grade-II glioma." (PMID 33954112, 2021). "Glioma-associated macrophages and microglia produce low levels of pro-inflammatory cytokines and lack expression of key molecules involved in T-cell co-stimulation, such as CD86, CD80, and CD40, indicating that they may be negative inducers of T-cell response in glioma." (PMID 37543576, 2023).
breast carcinoma (49 papers, 2003 to 2025). "In this work, consistent with the results of a previous study on breast cancer, we were unable to demonstrate an association between CD86 and RFS or OS." (PMID 40510346, 2025). "ZAG expression in breast cancer tissues was associated with decreased CD86 expression in Mφ; however, this association was not replicated in in vitro experiments." (PMID 38349455, 2024). "Lastly, monocytes isolated from individuals with early-stage breast cancer show decreased expression of key markers, including intercellular adhesion molecule 1 (ICAM-1; encoded by ICAM1), CD80 & CD86, and lower levels of TNF-α." (PMID 41550427, 2025). "Subsequently, we evaluated the impact of CD68, CD163, CD86, and PD-L1 expression in primary tumor tissues on overall survival, defined as the time from the initial breast cancer diagnosis to death." (PMID 40510346, 2025). "further showed that TAMs with high NRP2 expression, isolated from 4T1-derived murine breast cancer models, co-expressed both CD86 and CD206, whereas TAMs with low NRP2 expression were predominantly associated with high CD86 expression only." (PMID 40134439, 2025). "Breast cancer cells utilize CTLA-4 to physically remove CD80/CD86 from antigen-presenting cells via force-mediated trans-endocytosis." (PMID 41550427, 2025). "The percentage of CD86 ( +) B cells showed a positive relationship with higher tumor grade and higher numbers of involved lymph nodes in 44 breast cancer patients." (PMID 36797662, 2023). "An increased B cell activation (CD19+ MHC-II+ CD80/CD86+), as well as an increased antibody titer against the cancer cells, was observed in breast cancer tumor models." (PMID 35110563, 2022). "To examine associations between NRP expression and macrophage phenotype, we evaluated TAMs from mice bearing EO771 mammary tumors for putative markers of inflammation (CD86, iNOS) and wound-healing (CD206, Arginase-1) by flow cytometry." (PMID 35651620, 2022). "Mature DC membrane markers were analyzed by flow cytometry, and Mo-DCs obtained from breast cancer patients showed less HLA-DR, CD11c CD86, CD80, and CCR7 expressions when compared to Mo-DCs from healthy donors." (PMID 31827382, 2019). "In the PM-2 K+CD14+ cell population, the percentage of M1-like macrophages that were CCR7+CD86+ was significantly lower in patients with breast cancer than in healthy controls (p < 0.0001)." (PMID 29614988, 2018). "This study showed that LPS-stimulated human dendritic cells (DCs) decreased the expression of HLA-DR, CD83 and costimulatory molecules (CD40, CD80 and CD86) following coculturing with CTLA-4+ breast cancer cells." (PMID 28099147, 2017). "It has also been shown that TAMs show high expression of CD14 and to some extent expression of HLA-DR and CD86 in breast cancer." (PMID 28750018, 2017). "Our previous work in breast cancer patients has clearly demonstrated that such DCTs and DCTIs have an optimal antigen uptake capacity and upregulation of CD86, CD40 and class I, but low levels of CD83, as is expected of non-terminally mature DCs." (PMID 19298672, 2009). "In addition to the inverse correlation between Mφ and AZGP1/ZAG expression in breast cancer tissues, ZAG expression was associated with decreased CD86-positive cells in Mo/Mφ, thus suggesting that ZAG is involved in Mφ differentiation or its function." (PMID 38349455, 2024). "Furthermore, we found that, in breast cancer, the expression of three typical markers of TAMs (CD86, CSF1R, and CCR2) were positively correlated with SIPA1 and MYH9, respectively." (PMID 35453742, 2022). "Tan IIA was shown to inhibit breast cancer BT-20 cells by inhibiting the expression of PD-L1, cytotoxic T-lymphocyte-associated antigen 4 (CTLA-4), cluster of differentiation 80 [B7-1 (CD80)], and B7-2 (CD86)." (PMID 32265690, 2020). "The overall decrease of CD86 expression in M2a macrophages by breast cancer CM may contribute to immunosuppressive, tumor-promoting behavior." (PMID 26243145, 2015).
breast carcinoma (continued). "The increase in the CD86 expression during DC induction from monocytes was reproducible, both from the blood and regional tumour draining lymph nodes of patients with operable breast cancer." (PMID 18588665, 2008). "In our study, it was shown that the low-risk patients had significantly higher levels of PD-1, PD-L1, PD-L2, CD80, CD86, and CTLA-4 than the high-risk patients, suggesting this low-risk subpopulation of breast cancer patients might benefit more from immune checkpoint blockade therapy." (PMID 36936274, 2022). "In this breast cancer-focused review, we explore the interactions between autophagy and two clinically relevant immune checkpoint pathways; the programmed cell death-1 receptor with its ligand (PD-L1)/PD-1 and the cytotoxic T-lymphocyte-associated protein 4 (CTLA-4)/CD80 and CD86 (B7-1 and B7-2)." (PMID 36295867, 2022). "Next, we compared the expression of 27 primary breast cancers and their paired brain metastases for CD68, CD163 and CD86." (PMID 40510346, 2025). "The aim of this study was to compare the expression of CD68, CD86, CD163 and PD-L1 in breast carcinomas and their paired brain metastases." (PMID 40510346, 2025). "Cultures with lung cancer (A549), pancreatic cancer (PANC–1), and breast cancer (MDA-MB-231) were established and revealed similar results to the murine cultures regarding CD11c+/CD86+ cell populations." (PMID 39211033, 2024). "Meanwhile, inhibition of ApoE expression in THP-1 cells blocked the CD86 downregulation and the CD163 upregulation induced by breast cancer cells." (PMID 39695088, 2024). "CD86, a pro-inflammatory marker, was upregulated in both MMTV-Wnt1 mice bearing primary and secondary mammary tumors." (PMID 35382852, 2022). "that NDV infected MCF-7 cells have beneficial effects on the antigen presentation capacity of breast cancer patient derived dendritic cells demonstrated by an upregulation of CD40, CD80, CD83, CD86 and MHC class II (HLA-DR)." (PMID 34777344, 2021). "After 8 cycles of NAC, women whose breast cancers showed a PPR also had significantly lower levels of expression of mDC1 CD40 (p = 0.001) and CD86 (p = 0.001), compared with HFDs." (PMID 28913366, 2017). "Dendritic cells (DCs) obtained from peripheral blood and lymph nodes of patients with operable breast cancer are dysfunctional, with decreased expression levels of MHC Class II and CD86, and decreased IL-12 secretion." (PMID 28099147, 2017). "M1 markers (CD80 and CD86) showed a better correlation with markers of endothelial activation compared with total macrophage marker (CD68) and with M2 markers (CD163 and CD206) in breast cancer samples." (PMID 36248978, 2022). "We also showed by multiplex analysis that mRNA expression levels of compiled CD80/CD86, known receptors of CTLA-4, and PD-L1/PD-L2, known receptors of PD-1, demonstrated improved overall survival of patients with breast cancer, including all subtypes combined and with triple negative breast cancer." (PMID 35339889, 2022). "Furthermore, we further analysis the correlation of risk score and immune checkpoint in breast cancer and demonstrated that most of key checkpoint were significantly differentially expressed between the two groups in breast cancer patients, including CD44, TIGIT, CTLA4, CD274, CD86 and CD80." (PMID 35052427, 2021). "Also, THP-1 cells encountered breast cancer MDA-MB 231 cells those were pretreated with cisplatin and/or Oligo-Fucoidan expressed the higher mRNA levels of M0 (F4/80) and M1 (CD68 and CD86) marker." (PMID 32059469, 2020). "Therefore, we analyzed the presence of CD14+HLA-DRlow/-Co-receptorlow/- (i.e. negative for co-receptors such as CD86 and CD80) Mo-MDSCs in the peripheral blood of breast cancer patients." (PMID 25992611, 2015).
COVID-19 (48 papers, 2020 to 2026). A disease caused by infection with severe acute respiratory syndrome coronavirus 2. "Overall, PCA of classical monocytes revealed an acute-phase COVID-19 clustering pattern upon bacterial challenge, which was strongly associated with low expression of HLA-DR, CD86, CD80 and a high expression of CD163, CX3CR1 and CD11b." (PMID 35007290, 2022). "Our data support this hypothesis, including the depressed monocyte surface expression of HLA-DR and CD86 reported here, and our previously published data demonstrating that COVID-19 is associated with decreased LPS-induced TNF-alpha production by peripheral blood mononuclear cells." (PMID 35421120, 2022). "Furthermore, the persistent downregulation of CD86 and upregulation of PD-L1 expression in cDCs correlated with COVID-19 severity and could be associated with a reduced capacity to activate ‘naïve’ and memory Th cells in peripheral lymphoid tissue." (PMID 35632823, 2022). "Moreover, COVID-19 monocytes exhibited a similar profile as monocytes from patients with hepatitis C, in which upregulation of PD-L1 and IL-10, and downregulation of HLA-DR and CD86 were the hallmark of the infection." (PMID 33003471, 2020). "The importance of T-cell-mediated immunity in preventing COVID-19 death was particularly highlighted with the upregulation of Cd86, a T-cell co-stimulatory molecule in 6A2 mice with moderate mortality compared to 6A4 mice with severe mortality." (PMID 40242753, 2025). "There was a significant elevation in the expression of F4/80+iNOS+ and F4/80+CD86+ cells in response to COVID-19 EVs, indicating M1 macrophage polarization." (PMID 39475319, 2024). "Several studies have shown that the expression of CD86 on monocytes and dendritic cells was substantially decreased in patients with severe COVID-19." (PMID 38982354, 2024). "This contrasts with a previously published study, which showed long-term reduction in CD86 expression on pDC and HLA-DR+CD11c+ DC subsets in hospitalized COVID-19 patients." (PMID 36685582, 2022). "Taken together these data show that COVID-19 elicited lasting alterations in PD-L1 and CD86 expression levels on DC subsets." (PMID 36685582, 2022). "The hallmarks of severe COVID-19 forms are decreased levels of HLA-DR and CD86, as well as increased levels of CD163 in all subsets of circulating monocytes." (PMID 35632823, 2022). "In another study, COVID-19 monocytes exhibited an upregulation of PD-L1 and downregulation of HLA-DR and CD86, which were the hallmarks of the infection." (PMID 35458548, 2022). "A detailed analysis of the phenotype of various DC subpopulations in patients with severe COVID-19 revealed a decrease in HLA-DR and CD86 levels in all cell populations, except cDC1." (PMID 35632823, 2022). "The levels of expression of HLA-DR and CD86 on monocytes and mDCs were remarkably decreased in COVID-19 patients, which were more pronounced in severe patients." (PMID 33912590, 2021). "Monocyte clusters specific to severe COVID-19 patients (clusters 9 and 10), compared to the ones from patients with moderate disease (clusters 3, 5, and 17), had lower levels of HLA-DR and CD86." (PMID 33479167, 2021). "Higher levels of CD38 were detected specifically in moderately sick COVID-19 patients, while the maturation markers HLA-DR and CD86 were decreased over all DC subsets (with an exception for DC1s) in severe disease." (PMID 33479167, 2021). "Reduced expression of CD86 in circulating monocytes and cDCs has been described as a feature of severe COVID-19 but was also found in patients with less severe disease in our study." (PMID 34614036, 2021). "The baseline level of PD-L1 expression on COVID-19 monocytes and mDCs was increased compared to controls and the cells were unable to upregulate CD86, HLA-DR, and PD-L1 upon stimulation." (PMID 33003471, 2020).
COVID-19 (continued). "This work, too, demonstrated the reduction in CD86 and HLA-DR on monocytes and mDCs of COVID-19 patients, which was most pronounced in subjects with severe COVID-19 infection." (PMID 33003471, 2020). "In particular, we found an association between plasma proteins elevated in severe COVID-19, such as HGF, AREG, CKAP4, S100A12, NCF2, ITGB6, and a subpopulation of monocytes with lower expression of CD86 and HLA-DR, which are characteristics of myeloid-derived suppressor-like cells." (PMID 36829233, 2023). "A trend toward down-regulation of CD86 and HLA-DR was observed in HD + COVID-19 patients." (PMID 36675231, 2023). "Decrease populations of dendritic cells in severe COVID-19 with impaired CD86 and HLA-DR." (PMID 36072602, 2022). "CD86 expression on pDC was significantly increased at inclusion but returned, by 2 weeks, to a comparable level to controls and remained so for the remainder of the 6-7 months post-COVID-19." (PMID 36685582, 2022). "Interestingly, cDC isolated from COVID-19 patients fail to up-regulate HLA-DR, CD86 and PD-L1 in response to stimulation with TLR agonists." (PMID 33498725, 2021). "In vivo, severe COVID-19 patients, including children who experience a Kawasaki-like, multi-system inflammatory syndrome in response to the virus have reduced expression of HLA-DR and CD86 in cDC." (PMID 33498725, 2021). "Therefore, the level of CD80+- and CD86+-B cells in recovered COVID-19 should be studied to determine if those cells have a role in protecting the individuals from reinfection." (PMID 35069575, 2021). "Also, DCs exhibit a number of functional alterations in COVID-19, including reduced expression of CD86 and HLA-DR, whose upregulation is specifically hampered by MSCs during DC maturation." (PMID 34595175, 2021). "On the other hand, the frequency of HLA-DR+, CD86+ and CD91+ monocytes was dramatically reduced during COVID-19 and this contraction was directly proportional to the severity of the disease." (PMID 39136010, 2024). "In fact, in the severe COVID-19 patients and aging individuals, reduced numbers and altered activation of dendritic cells (DCs) were observed, with compromised CD80 and CD86 co-stimulatory molecules, which are necessary for T cell proliferation and activation." (PMID 37488118, 2023). "To this end, we identified an immune co-stimulator (CD86)-centered network, named stress-response core (SRC), which was robustly co-expressed in burns and COVID-19." (PMID 37488118, 2023). "Evaluation of M1/M2 phenotype markers CD86 and CD206 revealed CD206+ perivascular macrophages in both COVID-19 and control subjects." (PMID 36781876, 2023). "Upon bacterial challenge, classical monocytes from COVID-19 patients (acute- and rec-phase) displayed high expression of CD163 and CD11b, but low expression of the activation markers HLA-DR, CD86 and CD80." (PMID 35007290, 2022). "Moreover, reduced surface expression of the co-stimulatory CD86 and the antigen-presenting HLA-DR was noted for all three populations, with the most pronounced differences observed for the intermediate monocytes of COVID-19 patients and those of the control group." (PMID 35632823, 2022). "In lung, CD40, CD80, CD83 and HLA-DQA2 were upregulated while CD86 and FCER1A were decreased in mild COVID-19 as compared to healthy controls." (PMID 34502134, 2021). "Interestingly, MSCs from patients with mild COVID-19 transcribed high levels of CD86, HLD-DRA, HLA-DRB1, and HLA-DRB5, suggesting that these cells may play a role in the priming of T lymphocytes and act directly and indirectly in the orchestration of the immune response facing the disease." (PMID 35095855, 2021). "In our analysis, CD86 gene expression decreases and CD163 increases in CD16+ monocytes in severe cases of COVID-19 compared to healthy controls." (PMID 34108966, 2021).